INS (insulin)
Diseases named in the same sentence as INS in open-access papers (continued):
Sharing a sentence is not in itself a finding about the gene and the disease.
Insulin resistance (continued). "Pancreastatin may induce the impaired insulin secretion and insulin resistance in the setting of diabetes and/or obesity." (PMID 34204153, 2021). "Insulin resistance in muscle and adipose tissue leads to metabolic abnormalities such as inappropriate release of fatty acids through dysregulated lipolysis and disorders of glucose metabolism that further contribute to impaired insulin signaling." (PMID 34221261, 2021). "Third, this research has yet to test insulin level and Th1 cytokine levels of the participants, so it was not possible to assess the presence of insulin resistance, which is a major cause of obesity and its related metabolic diseases." (PMID 33541367, 2021). "High levels of FFAs may result either from the uptake of circulating FFAs, which are higher during fasting, or from accelerated adipose tissue lipolysis, which happens in insulin resistance, where the metabolic anti-lipolytic action of insulin is compromised." (PMID 34071499, 2021). "Although weight loss can improve insulin resistance and glycaemic control, as well as delay or prevent the need to initiate insulin, metformin does not consistently elicit large weight reductions." (PMID 33634589, 2021). "This pre-existing impairment should be considered in managing type 1 diabetic pregnancies in women with high pre-gestational BMI, since maternal overweight and obesity increase insulin resistance and insulin requirements especially during the second half of pregnancy." (PMID 33732212, 2021). "Alternatively, the decreased GLP-1 effect on insulin secretion could be in line with an increased insulin resistance state during the HFD, as also suggested by the metabolomics data in the present study." (PMID 34684324, 2021). "It will, therefore, be valuable to investigate the clinical benefits of thiamine therapy in the management of hepatic steatosis and of combination therapies using both thiamine and insulin sensitizers for management of FL disorders that involve insulin resistance, such as MAFLD." (PMID 33608323, 2021). "Case 2 was the only patient who had a normal weight, lacked acanthosis nigricans, and had a high HbA1c level, at diagnosis, and experienced a smaller increase in insulin secretion (only 25% of basal) and normal lipid profile at follow-up (in opposition to insulin resistance)." (PMID 33905625, 2021). "The main characteristics of T2DM are insufficient insulin secretion and insulin resistance." (PMID 33802741, 2021). "This change in insulin pulsatility may result in the downregulation of insulin action and indicates an interaction between dysregulated β-cell function and worsening of insulin resistance." (PMID 33387681, 2021). "Thus, the malfunction of β-cells through oxidative stress and the impaired response of peripheral tissues to insulin (insulin resistance) lead to a situation of hyperglycemia and hyperinsulinemia together with a chronic low-grade of inflammation." (PMID 34208379, 2021). "Furthermore, at the same time, peripheral insulin resistance occurs through blockage of the insulin signaling pathway and GLUT4." (PMID 34575946, 2021). "Furthermore, fasting PG levels in the 75-g OGTT correlated well with insulin resistance and secretion parameters only in the insulin therapy group." (PMID 33776619, 2021). "Therefore, insulin resistance, a hallmark of T2D, increases PAI-1 expression secondary to increased levels of insulin and its precursors." (PMID 33804680, 2021). "Mitochondria with mutation-associated energy deficiency cause insulin secretion impairment and insulinopenia.Nitric oxide (NO) impairment hinders vasodilation, altering the metabolic pathway of glucose and insulin to muscle tissue and thus contributing to insulin resistance." (PMID 34832987, 2021). "Insulin resistance in adipocytes eliminate insulin-induced repression of lipolysis." (PMID 34943836, 2021). "T2DM develops in case of insulin resistance and dysfunction of insulin secretion." (PMID 34834352, 2021).
Insulin resistance (continued). "After injected with D-gal at a dose of 150 mg/kg per day for 8 weeks, the insulin resistance was induced in normal diet fed rats as revealed by increased insulin level and HOMA index compared to NDV rats, and the SA-β-gal positive cells were significantly increased in NDDg rats." (PMID 33861726, 2021). "Inflammatory cytokines impair insulin signaling and trigger insulin resistance." (PMID 34650665, 2021). "Additionally, insulin resistance, common in sepsis patients, promotes lipolysis—insulin is an inhibitor of this process." (PMID 34072402, 2021). "They had significantly elevated fed plasma insulin levels, also demonstrated insulin resistance." (PMID 34409079, 2021). "However, studies have demonstrated that triglyceride, HDL-C, glucose intolerance, and insulin levels expectedly correlate best with insulin resistance." (PMID 34442386, 2021). "Because HOMA-IR is determined using both blood glucose and insulin levels, these data further support the hypothesis that HuRm−/− males display increased hallmarks of insulin resistance relative to controls only when fat mass is also increased." (PMID 34204316, 2021). "The reduction in insulin leads to a reduction in insulin resistance." (PMID 34447776, 2021). "A common link between T2DM and CVD is insulin resistance, or low insulin sensitivity." (PMID 34069950, 2021). "Finally, because men with early-onset androgenic alopecia were more insulin-resistant than body mass index-, plasma lipid- and blood pressure-matched peers, this state may predispose subjects to type 2 diabetes, metabolic syndrome, and other conditions associated with insulin resistance." (PMID 34064815, 2021). "Next, we analyzed fasting insulin (FINS) index that reflects insulin resistance." (PMID 34899339, 2021). "However, in an analysis of 606 Taiwanese individuals, 33 possessed the ASIC3 rs2288646A polymorphism and this was associated with a statistically significantly lower frequency of insulin resistance and lower fasting serum insulin levels." (PMID 33258401, 2021). "Moreover, BAT alleviates metabolic complications like dyslipidemia, impaired insulin secretion, and insulin resistance in type 2 diabetes." (PMID 33546400, 2021). "In this sense, increased insulin secretion in obese subjects appears associated with excess adiposity itself and not simply a compensatory response to insulin resistance." (PMID 33555509, 2021). "The synergistic effect of insulin resistance, insulin-induced weight gain, and increased diabetic duration might have contributed to the development of hypertension in this population." (PMID 34424924, 2021). "In the situation of increased insulin resistance, it is hypothesized that pancreatic beta cells produce more insulin to meet the demand which results in beta cell apoptosis and consequent increase of adipose tissues." (PMID 34200525, 2021). "Due to the association of GCP-4 with increased fasting insulin and HOMA-IR, we hypothesized an increase of GPC-4 during pregnancy due to the rising physiological insulin resistance and, potentially, a connection to GDM status." (PMID 34903856, 2021). "Obesity and insulin resistance are strongly implicated in the etiology of PCOS, and lifestyle modification, especially dietary modification and exercise, is the primary method to improve insulin sensitivity." (PMID 35185786, 2021). "Brain insulin resistance is commonly observed in early AD; as such, it has been proposed that therapy based on insulin sensitizer, diet or lifestyle, or insulin itself, may be a worthwhile approach." (PMID 34576151, 2021). "Likewise, COL11A2 exhibited higher methylation levels in the VAT of individuals with insulin resistance compared to normal insulin sensitivity controls." (PMID 33803198, 2021). "Additionally, BMI percentile has a significant predictive power for metabolic markers of insulin resistance (insulin value: AUC = 0.72, p < 0.001 and HOMA index: AUC = 0.68, p = 0.003)." (PMID 33924229, 2021).
Insulin resistance (continued). "In accordance with our findings, a double-blind randomized clinical trial showed that the administration of high doses of VITD in obese patients with peripheral insulin resistance or pre-DM increased the sensitivity to insulin and reduced the chance of progression of the condition to DM." (PMID 34578857, 2021). "In mice (C57BL/6), miR-375 blocks high-fat diet-induced insulin resistance and obesity, by inhibiting over-activation of the aryl hydrocarbon receptor and promoting hepatic expression of genes involved in responses to insulin, providing protection against the high-fat diet." (PMID 34203703, 2021). "There are two broad types of DM, named type 1 which progresses as a result of autoimmunity against the insulin-producing beta cells and type 2 characterized by variable degrees of insulin resistance, impaired insulin secretion, and increased hepatic glucose production." (PMID 33974654, 2021). "The notion that PI4KIIIβ upregulation by itself protects against lipid-induced insulin resistance in the heart, is demonstrated by the observations that PI4KIIIβ overexpression preserved insulin signaling and insulin-induced glucose uptake in lipid-overloaded cardiomyocytes." (PMID 33090289, 2021). "Furthermore, T2DM patients often develop insulin resistance, which is mainly manifested by abnormal insulin signals in the liver and muscles." (PMID 34691353, 2021). "In addition, the HOMA-β and fasting/post-challenge insulin levels were higher, whereas the Matsuda Index was lower, indicating insulin resistance with compensatory hyperinsulinemia in participants with snacking habits." (PMID 34578968, 2021). "ROS can impact insulin signal pathways, thus leading to consequent insulin resistance." (PMID 34497643, 2021). "Thus, ablation of PTP1B activity enhances both insulin and leptin signaling, leading to the mutual alleviation of obesity and insulin resistance." (PMID 33919569, 2021). "Elevated levels of pro-inflammatory cytokines such as IL-6 and TNF-α are usually related to insulin resistance and alteration of insulin sensitivity in diabetic patients, while they can also be used as markers of renal damage in relation to diabetic nephropathy." (PMID 34203479, 2021). "The increase in GAL could be due to the appearance of GAL tissue resistance or might be a compensatory mechanism against the insulin sensitivity increase observed in obese subjects suffering from insulin resistance." (PMID 33802616, 2021). "Moreover, defined as a condition called DIOS, even at mild levels of accumulation, hepatic iron load is related to NAFLD, hyperferritinemia, fasting insulin, insulin resistance, and other traits of the MetS." (PMID 34300354, 2021). "In T2DM, insulin resistance decreased glucose-stimulated insulin secretion, and glycosuria might protect against overnutrition by preventing accumulation and overloading of nutrients in different tissues." (PMID 34360753, 2021). "The authors proposed that the reduction in height velocity under leptin treatment may be due to the drop in insulin levels that follows the improvement in insulin resistance." (PMID 34002033, 2021). "Experimental evidence suggested that high nitrogen levels in the blood and elevated uric acid levels may increase insulin resistance and suppress insulin secretion." (PMID 33819181, 2021). "The separation of substances that mediate or mimic the action of insulin could lead to develop of novel structures which may be of clinical use in the treatment of glucose metabolism abnormalities associated with T2DM and insulin resistance." (PMID 34003397, 2021). "Impaired activation of GIPR and GLP-1R contributes to a decrease in the secretion of insulin and ghrelin and, on the contrary, to an increase in leptin and glucagon in the circulation, which contributes to the formation of insulin resistance in obese patients with T2DM." (PMID 33959145, 2021).
Insulin resistance (continued). "Thus, the lipoprotein-based marker LP-IR most likely reflects another mechanism of insulin resistance – adipose tissue insulin resistance – where the presence of high insulin levels impairs the suppression of lipolysis." (PMID 33613319, 2021). "Deletion of PTP1B potentiated insulin action and protected mice from diet-induced obesity and insulin resistance, suggesting that PTP1B is a negative regulator of some additional proteins such as the JAK2, a non-receptor tyrosine kinase activated by the leptin receptor." (PMID 33919569, 2021). "Moreover, a high level of expressed miR-29b was involved in repressing glucose uptake by insulin via the inhibition of Akt activity, which indicated insulin resistance." (PMID 34073649, 2021). "This decrease is proportional to the increase in BMI, insulin resistance and hemodilution, suggesting that hypoadiponectinemia could be involved in the development of the insulin-resistant state observed in late pregnancy." (PMID 34884524, 2021). "Both environmental (obesity, unhealthy diet and no physical activity) and genetic factors acquire several pathophysiological perturbations that lead to impaired glucose homeostasis in T2DM; therefore, insulin resistance and impaired insulin secretion are the key defects in T2DM." (PMID 34071497, 2021). "This aberrant adipose tissue metabolism in type 2 diabetes directly contributes to insulin resistance in target tissues through an increase in ectopic lipid accumulation or indirectly through the cytokine‐mediated disruption of the insulin signaling cascade in the liver and skeletal muscle." (PMID 33463892, 2021). "Among the existing treatments that address insulin resistance mainly used in diabetic patients, several clinical and pre-clinical studies have assessed the effect of insulin signaling-based approaches as potential mitigators of brain dysfunction and cognitive impairment." (PMID 33967682, 2021). "Inhibition of protein tyrosine phosphatase 1B (PTP1B) improves insulin sensitivity and therefore might protect against the development of obesity, insulin resistance, and insulin dysregulation—the common features of metabolic syndrome or type 2 diabetes." (PMID 34732209, 2021). "Although the pathogenesis of GDM remains largely unknown, the existing data suggested that the main defect of GDM is relatively diminished insulin secretion coupled with pregnancy-induced insulin resistance." (PMID 33661377, 2021). "Glucose tolerance tests and insulin tolerance tests were employed to assess insulin resistance." (PMID 34360761, 2021). "More recently, obesity was recognized as associated with increased basal and postprandial beta-cell insulin secretion even in the absence of insulin resistance." (PMID 33555509, 2021). "A crucial relationship between T2D and AD is observed in the context of chronic peripheral hyperinsulinemia and impaired insulin sensitivity being identified in patients with AD, though research on their translation to brain hyperinsulinemia and brain insulin resistance is in its infancy." (PMID 34497507, 2021). "With this background, in this paper, we analyzed whether the severe hepatic insulin resistance of inducible liver-specific insulin receptor knockout (iLIRKO) mice expands to the cardiovascular system, inducing insulin resistance in aorta artery and heart." (PMID 34440804, 2021). "Some studies show that cranberry products might promote glucose homeostasis by reducing fasting glycemia, improving homeostasis model assessment-estimated insulin resistance, increasing insulin sensitivity, and preventing compensatory insulin secretion." (PMID 34202412, 2021). "Nonetheless, central insulin resistance is closely associated with the progression of neurodegeneration, thus the most efficacious medications providing the greatest benefit are those that cross the BBB to enhance neuronal insulin signaling." (PMID 33925119, 2021).
Insulin resistance (continued). "It is plausible that the interactions of TGF β /Smad3 with PI3K/AKT singaling pathways led to impaired insulin signaling in the periphery, which may partly contribute to the insulin resistance in db/db mice." (PMID 33456576, 2021). "Moreover, swertiamarin attenuated insulin resistance by enhancing activation of insulin signalling and reducing inflammation in mice fed a HFD." (PMID 33794740, 2021). "Furthermore, diabetic rats fed with donkey milk powder for four weeks showed a significant decrease in blood glucose levels, increased insulin sensitivity and improved insulin resistance." (PMID 34445765, 2021). "In our study, there was a positive correlation between PV with insulin and insulin resistance." (PMID 34239023, 2021). "In the present study, we investigated the effects of different subfraction from maca extracts in regulating glucose metabolism in insulin‐resistant HepG2 cells and explored the active ingredients that might play a key role in regulating insulin resistance." (PMID 34136157, 2021). "Recently, one large sample of longitudinal study has shown that higher serum fasting insulin and insulin resistance could predict poorer verbal fluency and a steeper decline in verbal fluency." (PMID 34759889, 2021). "According to the literature and although body weight and fasting blood glucose were similar to normoxic mice, low‐fat diet mice exposed to chronic IH exhibited common features of systemic insulin resistance, such as increased fasting plasma insulin levels and impaired insulin sensitivity during ITT." (PMID 33682327, 2021). "Therefore, p300 has been proposed to be a prime factor leading to the development of hyperglycemia, impaired insulin levels and insulin resistance, which frequently occur in individuals treated with second-generation APs." (PMID 34483940, 2021). "T2D phenotypes such as glucose dyshomeostasis, insulin resistance, impaired insulin signaling, and systemic inflammatory cytokines have been shown to be involved in the progression of AD pathology by increasing amyloid-beta accumulation, tau hyperphosphorylation, and overall neuroinflammation." (PMID 33728019, 2021). "Second, the carbohydrates and fats from ultra-processed foods could interact with genes known to decrease insulin secretion and increase insulin resistance, enhancing their expression." (PMID 34206854, 2021). "The term “insulin resistance” (IR) has been used to explain why the glucose levels remain elevated even though there is no deficiency of insulin." (PMID 34447776, 2021). "Excessive insulin resistance or the inability to increase insulin production accordingly disrupts physiological modulation of pregnancy mediated glucose metabolism and may cause maternal gestational diabetes (GDM)." (PMID 34884524, 2021). "In addition, although FST correlates with insulin resistance in patients with T2D, the effect of insulin on reducing circulating FST is preserved in obese individuals and patients with T2D." (PMID 34385917, 2021). "Compensatory insulin secretion will eventually result in insulin resistance." (PMID 33806509, 2021). "The underlying mechanisms may involve stimulating glucose uptake by peripheral tissues, inhibiting endogenous glucose production, reducing insulin resistance, and stimulating islet β cells to release more insulin." (PMID 35095483, 2021). "Thus, HDACs can impart significant influence in both types of DM by regulating β cell viability, insulin production, insulin resistance, glucose intolerance, and inflammation." (PMID 34071497, 2021). "A Mediterranean diet, thanks to its compounds, reduces weight, body mass index, waist circumference, fasting insulin levels, homeostasis model assessment-insulin resistance, fatty liver indexes, triacylglycerides, fasting plasma glucose, and serum alanine aminotransferase." (PMID 35010923, 2021).